IL6ST (interleukin 6 cytokine family signal transducer)
Description:
Functions as a shared signal-transducing subunit not only for IL6 but also for other cytokine receptor complexes, including IL6, LIF, OSM, CNTF, IL11, CTF1, BSF3, MT-RNR2/humanin, CLCF1 and the heterodimeric complex CRLF1-CLCF1. Engages site 2 of CNTF, CLCF1, LIF, and IL-6, and site 3 of IL27 and IL6. Initiates signal transmission through three mechanisms. Binding of cytokines, such as IL6 or IL11 to the alpha-chains of their specific cell surface receptor triggers homodimerization of IL6ST/gp130. In contrast, binding of other IL-6 family cytokines can result in the formation of a IL6ST/gp130 heterodimer with another signal-transducing receptor, such as LIFR or OSMR. Moreover, binding of CNTF or CLCF1 or the heterodimeric complex CRLF1-CLCF1 or MT-RNR2/humanin to the non-signaling receptor CNTFR induces heterodimerization of the IL6ST/gp130 with LIFR or IL27RA/WSX1 (in the case of MT-RNR2/humanin). Mechanistically, homodimerization or heterodimerization of IL6ST/gp130 activate JAK tyrosine kinases bound to their intracellular domains. These kinases subsequently phosphorylate the homodimer or heterodimer form of IL6ST/gp130. The tyrosine phosphorylated signaling receptors serve in turn as docking sites for recruitment and activation of signal transducer and activators of transcription (STATs). The IL6 signaling pathway induces, in parallel, the expression of two cytokine receptor signaling inhibitors, SOCS1 and SOCS3, which inhibit JAK and terminate the activity of the IL6 signaling pathway as a negative feedback loop (By similarity). Also activates the yes-associated protein 1 (YAP) and NOTCH pathways to control inflammation-induced epithelial regeneration, independently of STAT3 (By similarity). Mediates signals which regulate immune response, hematopoiesis, pain control and bone metabolism (By similarity). Has a role in embryonic development (By similarity). Essential for survival of motor and sensory neurons and for differentiation of astrocytes (By similarity). Required for expression of TRPA1 in nociceptive neurons (By similarity). Required for the maintenance of PTH1R expression in the osteoblast lineage and for the stimulation of PTH-induced osteoblast differentiation (By similarity). Required for normal trabecular bone mass and cortical bone composition (By similarity). [Isoform 2]: Binds to the soluble IL6:sIL6R complex (hyper-IL6), thereby blocking IL6 trans-signaling. Inhibits sIL6R-dependent acute phase response. Also blocks IL11 cluster signaling through IL11R.
Synonyms: IL-6RB; gp130; CD130; sGP130; CDW130; HIES4; HIES4A; HIES4B; IMD94; STWS2
Tractability: Small molecule: it has a high-quality binding pocket. Antibody: an approved drug acts on it; UniProt places it where antibodies can reach, with high confidence; its Gene Ontology location is reachable by antibodies, with high confidence; UniProt predicts a signal peptide or a membrane-spanning region; the Human Protein Atlas places it where antibodies can reach. PROTAC: ubiquitination databases record sites on it; its protein half-life has been measured; a small molecule that binds it is known.
Target class: Membrane receptor
Gene: Protein-coding gene on chromosome 5 (55,935,095 to 55,995,022, reverse strand). Ensembl gene ENSG00000134352.
Subcellular location: Cell membrane (Isoform 1); Secreted (Isoform 2)
Subcellular location (Human Protein Atlas): Plasma membrane; Golgi apparatus; Predicted to be secreted
Pathways (Reactome):
Immune System: IL-6-type cytokine receptor ligand interactions; Interleukin-27 signaling; Interleukin-35 Signalling; Interleukin-6 signaling
Signal Transduction: MAPK1 (ERK2) activation; MAPK3 (ERK1) activation
Cell-Cell communication: Activation of STAT3 by cadherin engagement
Gene Ontology:
Molecular function: ciliary neurotrophic factor receptor activity; ciliary neurotrophic factor receptor binding; coreceptor activity; cytokine activity; cytokine receptor activity; growth factor binding; identical protein binding; interleukin-27 receptor activity; interleukin-6 binding; interleukin-6 receptor activity; interleukin-6 receptor binding; leukemia inhibitory factor receptor activity; oncostatin-M receptor activity; protein binding; scaffold protein binding; cytokine binding; signaling receptor activity; interleukin-11 binding; interleukin-11 receptor activity
Biological process: cell population proliferation; cell surface receptor signaling pathway via JAK-STAT; cell surface receptor signaling pathway via STAT; ciliary neurotrophic factor-mediated signaling pathway; cytokine-mediated signaling pathway; interleukin-11-mediated signaling pathway; interleukin-27-mediated signaling pathway; interleukin-6-mediated signaling pathway; intestinal epithelial cell development; leukemia inhibitory factor signaling pathway; negative regulation of neuron apoptotic process; oncostatin-M-mediated signaling pathway; positive regulation of adaptive immune response; positive regulation of cell population proliferation; positive regulation of Notch signaling pathway; positive regulation of osteoblast differentiation; positive regulation of T cell proliferation; response to cytokine; B cell differentiation; megakaryocyte differentiation; negative regulation of apoptotic process; negative regulation of T-helper 1 type immune response; positive regulation of acute inflammatory response; positive regulation of cardiac muscle hypertrophy; positive regulation of interleukin-10 production; and 4 more
Cellular component: ciliary neurotrophic factor receptor complex; extracellular exosome; extracellular region; humanin receptor complex; interleukin-6 receptor complex; membrane; membrane raft; oncostatin-M receptor complex; plasma membrane; receptor complex; external side of plasma membrane; cell body; dendrite; neuronal cell body
Genetic constraint (gnomAD): Loss-of-function variants: 8 observed, 38.78 expected, observed/expected ratio (o/e) 0.21, 90% interval 0.12 to 0.37. The upper end of that interval is the gene's LOEUF score, 0.37, which puts it in group 1 of 6, group 1 being the genes least tolerant of losing a copy. Missense variants: 409 observed, 502.14 expected, observed/expected ratio (o/e) 0.81, 90% interval 0.75 to 0.88. Synonymous variants: 161 observed, 180.83 expected, observed/expected ratio (o/e) 0.89, 90% interval 0.78 to 1.01.
Cancer hallmarks: tumour promoting inflammation (promotes); proliferative signalling (promotes)
Homologues: Orthologues: chimpanzee IL6ST (99% identical), macaque IL6ST (98% identical), pig IL6ST (92% identical), dog IL6ST (89% identical), rabbit IL6ST (87% identical), guinea pig IL6ST (81% identical), mouse Il6st (77% identical), rat Il6st (74% identical), tropical clawed frog il6st (46% identical). Paralogues in human: IL31RA (20% identical), CSF3R (17% identical), LIFR (16% identical), IL12RB2 (16% identical), OSMR (15% identical), LEPR (14% identical), IL12RB1 (12% identical), IL27RA (11% identical), IL23R (11% identical), PRLR (10% identical), CRLF1 (9% identical), GHR (9% identical), and 11 more.
Diseases named in the same sentence as IL6ST in open-access papers:
IL6ST is named in the same sentence as 184 diseases in open-access papers, as found by Europe PMC text mining. Sharing a sentence is not in itself a finding about the gene and the disease. The quoted sentences say what the papers report.
breast carcinoma (24 papers, 2005 to 2025). "Similar to this study, IL6ST has been shown to be downregulated in basal-like breast cancer compared to luminal A/B breast cancer subtypes and its lower expression was associated with poor overall survival in TNBC patients." (PMID 35387118, 2022). "On the other hand, rat chromosome 2q14 (which harbors Gpbp1, Map3k1 and Il6st) coincides with Mamtr3 (also known as Mcs1b or Mcs10), another mammary-cancer susceptibility QTL for which the COP allele confers resistance to chemically induced mammary carcinogenesis." (PMID 34388197, 2021). "The loss of IL6ST is involved in pathways related to lymphovascular invasion in breast cancer patients and its function has been associated with other physiologies such as myocardial and hematological development where embryos of mice deficient for IL6ST gradually die between 12.5 days post-coitum." (PMID 35387118, 2022). "When the correlation was made between ESR1 and IL6ST gene expression, they were positive in all breast invasive carcinoma subtypes, i.e., positive for Basal, Her2, Luminal A, and Luminal B breast cancer patients." (PMID 39201290, 2024). "On the other hand, the macrophage infiltration showed a positive correlation with IL1R1, IL1RAP, and IL6ST gene expression in all subtypes of patients with breast cancer." (PMID 39201290, 2024). "High expression of IL6ST, the gene coding for gp130, significantly improves the survival of patients suffering from breast cancer and metastatic melanoma." (PMID 36429126, 2022). "As a promising noninvasive indicator in breast cancer (BC), miR-188 has been shown to regulate BC cell viability and metastasis by interacting with IL6ST." (PMID 35466321, 2022). "Association of ANP32E, DSC2, IL6ST and ANKRD30A mRNA expression with clinicopathological features in breast cancer cases from the second cohort." (PMID 35387118, 2022). "Summary of studies reporting on the role of IL6ST as a biomarker in breast cancer, including study cohorts and main findings." (PMID 34210062, 2021). "Here we summarise how these cytokines exert their effect through the shared signal transducer IL6ST (gp130) and we review the extensive evidence on the role that different members of this family play in breast cancer." (PMID 34834425, 2021). "To date, 10 separate independent studies based on the analysis of clinical breast cancer samples have identified IL6ST as a predictor." (PMID 34210062, 2021). "Such a study also indicated that cytokines could inhibit and stimulate cell proliferation via IL6ST in breast cancer cells." (PMID 39201290, 2024). "IL6ST gene expression positively correlated with such infiltration in breast cancer Basal patients." (PMID 39201290, 2024). "In breast cancer, several studies highlighted IL6ST as a positive prognostic factor." (PMID 38987822, 2024). "In addition, a further 11 cytokines and receptors are connected via IL6ST as the node, which has also been reported as a prognostic biomarker in breast cancer." (PMID 38054018, 2023). "In addition, we showed that core fucosylation of integrin αvβ5 or IL6ST might be crucial for breast cancer cell adhesion to vitronectin or enhanced cellular signaling to interleukin 6 and oncostatin M, two cytokines implicated in the breast cancer epithelial–mesenchymal transition and metastasis." (PMID 35303925, 2022). "As a signal transducer, IL6ST could regulate multiple tumors development processes including head and neck squamous cell carcinoma, bladder cancer, hepatocellular carcinoma, gastric cancer, colorectal cancer, breast cancer, prostate cancer." (PMID 40040791, 2025). "Neutrophil infiltration had a direct relationship with the expression of IL1R1, IL1RN, IL1RAP, IL6ST, CXCL3, CXCL5, and CXCL6 in most of the subtypes of the breast cancer patients analyzed." (PMID 39201290, 2024). "We demonstrated that core fucosylation of IL6ST promoted IL-6– and OSM-stimulated cellular signaling important for breast cancer EMT and metastasis." (PMID 35303925, 2022).
breast carcinoma (continued). "As expected, this list contains numerous markers of breast cancer cells whose expression specificity was previously reported by other (notably ERBB3, XBP1, KRT18, IL6ST, CREB1, TFF1, TFF3)." (PMID 19104654, 2008). "The KM survival curves showed that CD46, JAG1, IL6, and IL6R were all risk factors that lead to poor prognosis in breast cancer patients, which implies that the enhanced interaction between CD46-JAG1 leads to poor prognosis in breast cancer patients, along with the IL6-(IL6R+IL6ST) axis." (PMID 38571938, 2024). "Gene expression associated with ER status in breast cancer patients was analyzed and results indicated that IL1R1 and IL1RN gene expression levels were non-significant among patients, whereas those with high IL6ST expression levels had a positive ER status." (PMID 39201290, 2024). "However, IL1RN, IL6ST, CXCL3, CXCL5, and CXCL6 gene expression levels were non-significant concerning clinical survival of breast cancer patients." (PMID 39201290, 2024). "However, IL1RN, IL6ST, CXCL3, CXCL5, and CXCL6 gene expression levels were non-significant concerning clinical survival of breast cancer patients according to the Cox proportional Hazard model." (PMID 39201290, 2024).
COVID-19 (16 papers, 2020 to 2025). A disease caused by infection with severe acute respiratory syndrome coronavirus 2. "In this context, polymorphisms at IL6, IL6R, and IL6ST genes become interesting candidates to be prognostic and predictive markers of COVID-19 severity." (PMID 37243282, 2023). "Hence, the present study aims to evaluate the role of polymorphisms at IL6, IL6R, and IL6ST in COVID-19 severity aspects, along with their influence on IL-6 plasma levels during active COVID-19." (PMID 37243282, 2023). "In conclusion, this study revealed that the NTD region of the COVID-19 Spike protein had a high CDOCKER interaction energy with IL6ST using network pharmacology and molecular docking analysis." (PMID 34731090, 2021). "The results showed that IL6R/IL6/IL6ST (PDB ID: 1P9M) had high level of CDOCKER interaction energy with the Spike protein of COVID-19 (PDB ID: 6VXX)." (PMID 34731090, 2021). "Moreover, IL6ST gene mutations can cause Hyper-IgE recurrent infection syndrome-4B, a rare recessive immunologic disorder, highlighting IL6ST as a promising candidate gene for COVID-19." (PMID 37243282, 2023). "Hence, the evaluation of the influence of polymorphisms in key genes of the IL-6 pathway, namely IL6, IL6R, and IL6ST, may provide valuable prognostic/predictive markers for COVID-19." (PMID 37243282, 2023). "Therefore, IL6ST is involved in the process by which COVID-19 enters the cell." (PMID 34731090, 2021). "Then, through an extended MR study design, we sought to strengthen the evidence for a causal relation of blood levels of IL-6 pathway components, including IL-6, sIL6R, soluble IL6ST (also called gp130), and CRP, on COVID-19 outcomes." (PMID 39062668, 2024). "IL6R and IL6ST genes, respectively, in 227 COVID-19 patients (132 hospitalized and 95 non-hospitalized)." (PMID 37243282, 2023). "Nonetheless, these gene expression patterns may suggest a link between tocilizumab effects, IL6R, IL6ST, and S100A8/9 in COVID-19 patients." (PMID 35064122, 2022). "Protein-protein docking between COVID-19-Spike and IL6 receptor (IL6R)/IL6/IL6 receptor subunit beta (IL6ST) was simulated to verify whether IL6, the core target identified through our network pharmacology-based approach, was a pathogenic target." (PMID 34731090, 2021).
rheumatoid arthritis (10 papers, 2013 to 2024). A chronic, systemic autoimmune disorder characterized by inflammation in the synovial membranes and articular surfaces. "Variants in IL6ST have been associated with rheumatoid arthritis and multiple myeloma, but also with components of metabolic syndrome." (PMID 23382691, 2013). "Finally, we found that increased IL6ST expression in T cells and whole blood is predicted to increase the risk of rheumatoid arthritis, systemic connective tissue disorders, polyarthropathies, other arthritis, autoimmune diseases, and polymyalgia rheumatica." (PMID 39563277, 2024). "There is currently no clinical relevance of common variants in the IL6ST locus, although it is noticeable that several of the disorders such as Crohn’s disease and rheumatoid arthritis associated with the rs7731626 (5-56148856-G-A) variant affect IL6ST expression." (PMID 38133879, 2023).
autoimmune disease (9 papers, 2019 to 2025). A disorder resulting from loss of function or tissue destruction of an organ or multiple organs, arising from humoral or cellular immune responses of the individual to their own tissue constituents. "IL6ST is linked to RA, multiple sclerosis, autoimmune diseases, inflammatory bowel diseases, pneumonia, and Crohn’s disease, and is regulated by multiple drugs and phosphorylated by CDK6." (PMID 40839671, 2025). "Mutations of IL6ST in mice can result in a hyper-responsive T cell phenotype, and development of an arthritis-like autoimmune disease in mice." (PMID 36268024, 2022). "As ANKRD55’s proximate neighbor, IL6ST is especially striking due to its well-documented role in inflammation and autoimmune disease." (PMID 35111166, 2021). "Risk for autoimmune disease conferred by rs7731626 is correlated with increased mRNA expression of ANKRD55 and IL6ST and with reduced cis CpG methylation in CD4+ T cells." (PMID 35111166, 2021). "The IL6ST gene is near ANKRD55, and IL-6 is more attractive for its precise role in inflammation and autoimmune disease." (PMID 35983018, 2022). "Many of these genes have either known roles in Treg differentiation, stability and function (CD48, IL6ST, EZR, ELMO1, IL18R1), or altered expression in human Treg in autoimmune disease (SLAMF1, ANKRD55, TAGAP)." (PMID 35773720, 2022).
asthma (7 papers, 2020 to 2026). "Asthma was noted in 3.7%, with a high prevalence in patients with CARD11 (AD DN) or Interleukin 6 cytokine family signal transducer (IL6ST) deficiency." (PMID 41142799, 2025). "We further investigated the potential role and clinical relevance of upregulated WTAP in the progression of inflammatory diseases, and revealed that both WTAP and IL6ST were upregulated in patients with SLE, asthma, sepsis, RA, psoriasis, and IBD." (PMID 39007267, 2024). "For example, strong evidence is found for site-specific DNAm as an intermediary via which disease variants regulate ORMDL3, GSDMB, and JAZF1 expression by CD4+ T cells in RA, MS, and asthma, and a similar mechanism in relation to ANKRD55 and IL6ST is limited to RA and MS." (PMID 31945409, 2020).
craniosynostosis (7 papers, 2017 to 2025). Craniosynostosis is defined as the premature fusion of one or more cranial sutures leading to secondary distortion of skull shape resulting in skull deformities with a variable presentation. "We describe a homozygous non-synonymous variant in IL6ST (p.R281Q) in a patient with craniosynostosis and retained deciduous teeth." (PMID 32566365, 2020). "A second patient with homozygous IL6ST p.R281Q with pan-craniosynostosis was recently identified (Mcmanus & Bhoj, personal communication)." (PMID 38133879, 2023). "In a recent study, a biallelic non-synonymous variant in IL6ST (gp130), which results in a loss of IL11-signaling, conferred a craniosynostosis phenotype, which replicated in a mouse model, although again this phenotype is mediated at the membrane receptor level." (PMID 34239012, 2021). "In contrast to individuals with partial LOF IL6ST mutations, complete IL11RA deficiency, or STAT3-DN mutations, individuals with IL6ST-DN do not exhibit craniosynostosis, most likely because of remaining functionality in IL-11 signaling." (PMID 40040707, 2025).
gastric cancer (7 papers, 2016 to 2025). A primary or metastatic malignant neoplasm involving the stomach. "The IL-6/STAT3 signaling pathway has been investigated in gastric cancer research, and activation of IL6ST enhances carcinogenesis." (PMID 33995063, 2021). "We used this dataset to evaluate the expression patterns of YAP1, STAT3, IL11, IL6, TEAD1, IL6ST, and IL11RA in gastric cancer patients within the four TME subtypes." (PMID 37957015, 2024).